ENSG00000212293
Synonyms: LOC124903256
Gene: Small nucleolar RNA gene on chromosome 13 (32,420,390 to 32,420,516, reverse strand). Ensembl gene ENSG00000212293.
Gene Ontology:
Biological process: RNA processing
Cellular component: nucleolus
Homologues: Orthologues: mouse Gm24896 (57% identical), rat Snora16b (53% identical). Paralogues in human: SNORA16A (66% identical), SNORA16B (64% identical).